TLR4 (toll like receptor 4)
Diseases named in the same sentence as TLR4 in open-access papers (continued):
Sharing a sentence is not in itself a finding about the gene and the disease.
lipidosis (2 papers, 2015 to 2022). "In conclusion, ApoE deficiency acts synergistically with a WD to trigger lung lipidosis and inflammation at least in part via TLR4 signaling." (PMID 25975841, 2015). "The present study demonstrated that ApoE deficiency in combination with a WD induces lipidosis and chronic inflammation in lungs through the TLR4 pathway." (PMID 25975841, 2015). "The pathogenesis of the ApoE knockout combined with a HFD also results in lipidosis and inflammation in lung tissue through the toll-like receptor 4 (TLR4) pathway." (PMID 35172845, 2022). "TLR4 in macrophages is critical in pulmonary inflammation and lipidosis." (PMID 25975841, 2015). "Blocking the TLR4 pathway was able to ameliorate lipidosis and inflammation in the ApoE−/− WD mice." (PMID 25975841, 2015). "The results of the present study showed that TLR4 signalling activated the MyD88/NF-κB and the TRIF/IRF3 pathway to elicit lung inflammation and lipidosis in the ApoE−/− WD mice." (PMID 25975841, 2015). "Of note, it was found that the blocking of TLR4 could not fully ameliorate lipidosis and inflammation, suggesting that other signaling pathway(s) may be involved in those pathomorphological changes." (PMID 25975841, 2015).
Lymphadenopathy (2 papers, 2011 to 2019). Enlargement (swelling) of a lymph node. "This also suggests that the lymphadenopathy, whilst caused by LPS, is not driven through TLR4, a novel finding in this context." (PMID 30972059, 2019).
macrophage activation syndrome (2 papers, 2020 to 2021). A complication of rheumatic disease that is caused by excessive activation and uncontrolled proliferation of T lymphocytes and well-differentiated macrophages. "The mechanism of hypercytokine storm from HLH resembling macrophage activation syndrome infers that the absence of BTK can augment inflammation cytokines through Toll-like receptor signaling pathways (TLR4, 7, 8, and 9), possibly driving to the HLH process as two brothers in a previous report." (PMID 33013854, 2020).
male infertility (2 papers, 2021). The inability of the male to effect fertilization of an ovum after a specified period of unprotected intercourse. "Collectively, our data showed that administration of PEA-um revealed a key role of PPAR-α and TLR4 in varicocele pathophysiology, unmasking new nutraceutical therapeutic targets for future varicocele research and supporting surgical management of male infertility." (PMID 33668991, 2021).
meningoencephalitis (2 papers, 2021 to 2024). Inflammation of the meninges and brain, generally secondary to an infectious cause. "In addition, E. coli can cause meningoencephalitis by increasing the inflammatory response and activating the TLR2/TLR4/MyD88 and the NLRP3 inflammasome pathways." (PMID 35145923, 2021). "The study evaluates the critical role of Cav-1 regulation through the TLR4/MyD88 signaling pathway, modulates tight junction proteins, influences BBB permeability, and contributes to brain damage in A. cantonensis-induced meningoencephalitis." (PMID 38922036, 2024).
Merkel cell carcinoma (2 papers, 2022 to 2023). "The TLR4 agonist G100 is a fully synthetic analogue of bacterial lipopolysaccharides (LPS) and has been tested intratumorally in patients with Merkel cell carcinoma; because TLR4 is involved in septic shock, systemic administration of its agonist could be dangerous." (PMID 38006049, 2023).
metastasis (2 papers, 2010 to 2024). The spread or migration of cancer cells from one part of the body (where they first appeared) to another. "The high expression of TLR4 was significantly associated with liver metastasis (P=0.0001) and TNM stage (P=0.0197) and potentially related to peritoneal metastasis (P=0.0611)." (PMID 20145615, 2010). "Moreover, the study has specified that Metastasis-Related Lung Adenocarcinoma Transcript 1 could regulate the expression of Toll-like receptor 4 (TLR4) with increased cell proliferation and migration in PASMCs." (PMID 38194707, 2024). "In addition, CRC with liver metastasis showed higher levels of TLR4 and MyD88 expression than did CRC without liver metastasis (P=0.0015, P=0.0035, P=0.0001, respectively)." (PMID 20145615, 2010).
metastatic cancer (2 papers, 2020 to 2022). A carcinoma which has spread from the original site of growth to another anatomic site. "However, other studies have pointed out that LY96 inhibition would prevent TLR4-mediated inflammatory responses and metastatic cancer growth." (PMID 36429083, 2022). "We hypothesized that blocking MD2 using a specific inhibitor would prevent TLR4-mediated inflammatory responses and metastatic cancer growth." (PMID 32210720, 2020).
middle ear infection (2 papers, 2021 to 2022). "This analysis showed that the expression of Tlr4, minimal prior to middle ear infection, was seen primarily in the epithelium, endothelium, and PMNs at 6 h, epithelium, monocytes/macrophages, and PMNs at 1d, and restricted to monocytes by 2d." (PMID 36092940, 2022).
monocytic leukemia (2 papers, 2021 to 2024). "This is an interesting observation, as LPS has been shown to induce miR-146a expression in human monocytic leukemia cells, via binding to TLR4, triggering an intracellular signaling pathway that results in activation of NF-κB and subsequent miR-146a upregulation." (PMID 33790910, 2021). "Induced by LPS in the human monocytic leukemia cell line THP-1, NEAT1 enhances inflammatory responses by sponging miR-17-5p, thereby stabilizing TLR4 mRNA (the miR-17-5p/TLR4 axis)." (PMID 38473915, 2024).
mood disorder (2 papers, 2024). A cognitive disorder a disturbance in which the person's mood is hypothesized to be the main underlying feature. "Mechanistically, the TLR-4/NF-κB and NLRP3 inflammasome signaling pathways partially mediate this interaction, highlighting the intricate relationship between gut microbiota, inflammation, and mood disorders." (PMID 39741947, 2024).
mycobacterial infection (2 papers, 2012 to 2022). "Similar to TLR2, deficient TLR4 function is generally associated with increased susceptibility to mycobacterium infection." (PMID 22529866, 2012). "However, a number of functionally deficient polymorphisms in TLR1 and TLR4 have been found to confer protection to mycobacterial infection." (PMID 22529866, 2012). "In mammals, TLR4 plays a role in defense against mycobacterial infection." (PMID 35205112, 2022). "Compared with TLR4, the function of TLR2 in mycobacterial infection is more complex, because TLR2 can recognize a large number of components on a mycobacterial membrane." (PMID 35205112, 2022). "It indicates that TLR2 and the other TLRs compensate for the lack of TLR4 function in mycobacterial infection." (PMID 35205112, 2022).
Mycoplasma infection (2 papers, 2020). "TLR4 is generally associated to the recognition of lipopolysaccharide antigen (LPS), but it has also been reported to be involved in mycoplasma infections, triggering the production of pro-inflammatory mediators involved in the immune response to bacterial infection." (PMID 32292794, 2020). "Although Mycoplasmas do not have cell wall, several researchers reported the relationships between TLR4 and the inflammation during Mycoplasma infection." (PMID 32154274, 2020).
myeloid malignancy (2 papers, 2021 to 2023). "As it has been reported that MSCs of myeloid neoplasms can be therapeutically targeted using epigenetic drugs such as azacytidine (AZA), we finally treated HS-5 stromal cells for 72 h with AZA to evaluate its effect onto mH2A1.1/TLR4 axis." (PMID 37852977, 2023).
myeloproliferative neoplasm (2 papers, 2020 to 2022). A clonal hematopoietic stem cell disorder, characterized by proliferation in the bone marrow of one or more of the myeloid (i.e., granulocytic, erythroid, megakaryocytic, and mast cell) lineages. "We previously reported that heterodimeric S100A8/9 inhibits ERK1/2 signaling mediated by Toll-like receptor 4 (TLR4) in myeloproliferative neoplasms." (PMID 35805957, 2022). "In lung injuries, S100A8 transduces its signal via TLR4 and is not mediated by RAGE, which sometimes functions as an inhibitory receptor of AKT proliferation signaling in myeloproliferative neoplasms." (PMID 32903598, 2020).
nematode infection (2 papers, 2020 to 2023). "The model analyses revealed that the variance in nematode infection intensity was best explained by TLR4_Ht1 and the landscape with a delta AICc >2 compared to all other genetics & landscape models." (PMID 32616896, 2020).
non-Hodgkin lymphoma (2 papers, 2021 to 2022). Distinct from Hodgkin lymphoma both morphologically and biologically, non-Hodgkin lymphoma (NHL) is characterized by the absence of Reed-Sternberg cells, can occur at any age, and usually presents as a localized or generalized lymphadenopathy associated with fever and weight loss. "Five studies examined the association of TLR4 polymorphism rs4986790 with PC, and six studies for non-Hodgkin’s lymphoma." (PMID 36281200, 2022). "Other tumors linked to TLR4 genetic variants include HCC, prostate cancer, CRC, and non-Hodgkin lymphoma (NHL)." (PMID 33763088, 2021).
non-melanoma skin carcinoma (2 papers, 2021 to 2024). "In this study, we examined the association between TLR4 SNPs, mainly D299G and T399I, and the risk of non-melanoma skin cancer (NMSC) in a cohort from the University of Alabama at Birmingham." (PMID 39684439, 2024). "Our data provide further evidence that activation of the TLR4 pathway promotes the development of UV-induced non-melanoma skin cancer mediated at least in part on its negative effects on DNA damage." (PMID 34771569, 2021).
opioid dependence (2 papers, 2014 to 2025). "A clear understanding of direct links from xenobiotic-TLR4-NF-κB signalling to sympathoadrenal tone and hypothalamic lifespan control has the potential to revolutionise the direction of therapeutic endeavours in the treatment of opioid dependence." (PMID 24889849, 2014).
opioid use disorder (2 papers, 2021 to 2022). A substance-related disorder that involves the recurring use of opioids despite negative consequences. "Regarding technical limitations of our investigations, functional responses to LPS were not examined, and we are unable to conclude if AUD is associated with a change in innate responses to TLR-4 stimulation, as we recently reported among PLWH with opioid-use disorder." (PMID 35371104, 2022).
oral epithelial dysplasia (2 papers, 2014 to 2020). "Clinical studies have shown a significantly higher expression of TLR4 and MyD88 in oral epithelial dysplasia and OSCC." (PMID 33002094, 2020).
oral mucositis (2 papers, 2021 to 2025). Inflammation of the mucous membranes of any of the structures in the mouth. "Lipopolysaccharides (LPS) produced by Gram-negative anaerobes could induce inflammatory responses by activating toll-like receptor 4 signaling pathway, which may contribute to the development of oral mucositis." (PMID 34149727, 2021).
orchitis (2 papers, 2021 to 2024). Inflammation of one or both testes due to viral or bacterial infections. "OXY could also decrease pro-inflammatory cytokines levels and boost anti-inflammatory by downregulating TLR4, MyD88, NF-κB, and PK2/PKR1 pathways, which are linked to LPS-induced orchitis." (PMID 39845795, 2024).
parasite (2 papers, 2019 to 2021). "This led us to further investigate the effect of Neu1 silencing on TLR4 during this parasite infection." (PMID 31649671, 2019). "Such events strongly confirm the importance of Neu1 in modulation of TLR4 sialylation during parasite infection resulting in impairment of innate immune response." (PMID 31649671, 2019). "Here, we have established a specific novel role of a mammalian lysosomal sialidase (Neu1) on the regulation of TLR4 sialylation and its impaired functioning during this parasite infection." (PMID 31649671, 2019).
pemphigus (2 papers, 2020 to 2021). Pemphigus is a group of rare autoimmune diseases that cause blistering of the skin and mucous membranes (mouth, nose, throat, eyes, and genitals).This conditioncan occur at any age, but often strikes people in middle or older age. "Additionally, a study in a Chinese cohort in different intraepidermal bullouse diseases showed a relocalization of tlr4 expression sites with increased expression in pemphigus and BP lesions." (PMID 33204706, 2020).
Peptic ulcer (2 papers, 2015 to 2025). The term peptic ulcer refers to acid peptic injury of the digestive tract, resulting in mucosal break reaching the submucosa. "In our study, the risk of peptic ulcer was increased in the TLR4 homozygous wild types and it persisted also after accounting for other risk factors with multivariate analyses." (PMID 26161647, 2015). "Our results suggest a role for Toll-like receptor 4 in gastric acid regulation and that the Toll-like receptor 4 +896 and +1196 wild type homozygozity increases peptic ulcer risk via gastrin secretion." (PMID 26161647, 2015). "Additionally, we report an increased risk for peptic ulcer for the TLR4 +896/+1196 homozygous wild type patients over the double mutant polymorphism carriers, which is physiologically appropriate considering the G17 results." (PMID 26161647, 2015). "There is only one study reporting an association between these TLR4 polymorphisms and peptic ulcer." (PMID 26161647, 2015). "We speculate that TLR4–ligand interaction in G and D cells could have a direct effect in the gastrin and somatostatin secretion, respectively, and potentially explain the associations between the TLR4 polymorphisms and increased serum gastrin and the peptic ulcer risk." (PMID 26161647, 2015). "We hypothesized that TLR4 could affect gastrin levels and thereby affect peptic ulcer pathogenesis also in human subjects." (PMID 26161647, 2015). "Previous reports have shown contradictory associations between the TLR4 +896 and +1196 polymorphisms and H. pylori related gastritis and peptic ulcer and have not presented a clear physiological mechanism for the polymorphisms in their pathogenesis." (PMID 26161647, 2015). "Previously, in patients with clear evidence of peptic ulcers, H. pylori infection showed a significant increase in TLR2 and TLR4 mRNA expression in the antral region compared to uninfected samples." (PMID 40362298, 2025).
polymyositis (2 papers, 2016 to 2017). A rare idiopathic inflammatory myopathy characterized by symmetric proximal muscle weakness and elevated muscle enzymes. "To determine the possible role of TLR4 in polymyositis (PM) development, we collected muscle samples from PM patients and mice subjected to an experimental autoimmune myositis (EAM) model." (PMID 28446897, 2017).
primary immunodeficiency (2 papers, 2023 to 2024). "Furthermore, KEGG pathway enrichment analysis demonstrated that the differentially expressed genes were mainly enriched in signaling pathways such as primary immunodeficiency, B lymphocyte receptor, chemokine, Fc-γR, FC-Epsilon RI, and TLR4/NF-κB." (PMID 39308975, 2024).
prostate adenocarcinoma (2 papers, 2021). "Increased expression of TLR4 is also apparent in prostate adenocarcinoma samples compared to normal prostate tissue." (PMID 33554122, 2021).
proteinopathies (2 papers, 2017 to 2020). "The proteopathy of FLNA enables a second toxic signaling pathway of Aβ: its activation of the innate immune receptor TLR4." (PMID 34295950, 2017). "By reversing the FLNA proteopathy, PTI-125 dramatically reduces FLNA’s aberrant linkages to both α7nAChR and TLR4, consequently reducing tau hyperphosphorylation and neuroinflammation." (PMID 34295950, 2017).
pulmonary edema (2 papers, 2017 to 2020). Accumulation of fluid in the lung tissues causing disturbance of the gas exchange that may lead to respiratory failure. "Tlr4 deficiency improved lethality rate, PaO2, and pulmonary edema, and prevented the endothelial and neutrophil activation caused by Cl2 exposure." (PMID 33062035, 2020). "Tlr4 deficiency improved lethality rate, blood gas, and pulmonary edema, and prevented endothelial and neutrophil activation caused by Cl2 exposure." (PMID 33062035, 2020).
pulmonary embolism (2 papers, 2022 to 2025). The obstruction of the pulmonary artery or one of its branches by an embolus, sometimes associated with infarction of the lung. "In an acute pulmonary embolism in vivo model and cellular experiments with human pulmonary artery endothelial cells, Cts treatment was found to abolish thrombin-induced inflammation blocking TLR-4 expression and p38 phosphorylation, decreasing the consequent acute pulmonary embolism." (PMID 36297449, 2022). "Our experiments indicate that in the acute pulmonary embolism combined with shock model, the TLR4/NF-κB/HIF-1α signaling pathway is activated, which might stimulate the upregulation on the expression of downstream Gal-3, and the release of inflammatory factors such as IL-6 and TNF-α." (PMID 40666114, 2025). "Similarly, our experiment verifies that severe spasm of the pulmonary artery might damage the vascular endothelial cells, reduce the release of NO, activate the expression of TLR4/NF-κB pathway as well as Gal-3 in the acute pulmonary embolism combined with shock model." (PMID 40666114, 2025).
pyometra (2 papers, 2020 to 2025). "Specifically, uterine TLR-4 transcription is upregulated 2.4-fold in cases of pyometra compared to the DE phase of the estrus cycle." (PMID 41150074, 2025). "Escherichia coli and its LPS activate TLR-4 signaling initiating inflammatory cascades that lead to pyometra pathogenesis on uterine epithelial, stromal, and resident immune cells." (PMID 41150074, 2025). "In cases of pyometra, the surface epithelium exhibits higher TLR-4 expression than the stroma, glandular epithelium, or healthy uterus." (PMID 41150074, 2025).
relapsing-remitting MS (2 papers, 2016 to 2019). "Increased levels of IL-23 correlate with increased levels of MMPs as detected in mouse models such as TLR4 knock-out mice and in human peripheral blood of patients with relapsing-remitting multiple sclerosis." (PMID 27446965, 2016). "We utilized prospectively collected serum from relapsing-remitting MS patients (n = 18) and controls (n = 16) and confirmed lower concentration of TLR3 and higher concentration of mechanistically related TLR4 in MS EVs compared to controls." (PMID 31509962, 2019).
renal carcinoma (2 papers, 2020 to 2024). A carcinoma arising from the epithelium of the renal parenchyma or the renal pelvis. "TLR4, OPRL1, and OGFR opioid receptor genes have been reported to be associated with renal cancer progression." (PMID 38352696, 2024). "Interestingly, it has been already shown that miR-216a targets TLR4 in renal cancer, corroborating our hypothesis." (PMID 32230799, 2020).
rhabdomyolysis (2 papers, 2020 to 2021). Necrosis or disintegration of skeletal muscle often followed by myoglobinuria. "Inflammation is the main pathogenic feature of AKI induced by rhabdomyolysis, and previous studies have shown that pattern recognition receptors such as TLR4 and NLRP3 are upregulated in the kidney in RIAKI." (PMID 33202867, 2020). "TLR4 has been proposed as a biomarker of rhabdomyolysis-AKI." (PMID 33467524, 2021).